CAT (catalase)
Diseases named in the same sentence as CAT in open-access papers (continued):
Sharing a sentence is not in itself a finding about the gene and the disease.
Obesity (continued). "They found an increase in OS markers, and high activity of catalase and SOD in placentas from women with obesity." (PMID 31312657, 2019). "Our results showed that the obesity induced significant reductions of intratesticular SOD, catalase, GSH-Px activities and total anti-oxidant capacity (T-AOC) level, and the content of reduced glutathione (GSH) compared with the Ctr group." (PMID 31443330, 2019). "People with obesity display different response in several CV, BV, and AV after a nutritional intervention, depending on the antioxidant genetic background of SOD and CAT enzymes." (PMID 29339975, 2018). "To investigate the mechanisms of low testosterone levels induced by the joint exposure to obesity and DEHP, we determined some markers of oxidative stress: MDA, T-AOC, SOD, GSH, H2O2, CAT, and GSH-PX expression." (PMID 29887939, 2018). "At 12 weeks, obesity and DEHP had reduced CAT levels to 88%, 90%, 89%, 83%, and 71% of the controls in the DEHP, DIO, DIO + DEHP low, DIO + DEHP middle, and DIO + DEHP high mice, respectively (P < 0.01)." (PMID 29887939, 2018). "This study is a first step towards the identification of biomarkers for early-stage obesity (GSTT1, GSTT3, GSTM1, MGST1, MGST3, SOD2, CAT) and glucose load (CRYM) in cattle." (PMID 30235219, 2018). "The level of antioxidant enzymes like catalase, and SOD activities and GSH concentration in the liver of HCHF diet fed rats were seen significantly lower than control group which signifies that obesity has reduced the antioxidant capacity of the liver cells." (PMID 28806968, 2017). "According to previous reports, melatonin supplementation significantly improves antioxidant status by increasing the activity of antioxidant enzymes (i.e., superoxide dismutase, glutathione peroxidase, catalase, etc.)in T2DM and obesity." (PMID 28604593, 2017). "In obesity, incubation with SOD and catalase attenuated PVAT-intact vessel contractility in the presence and absence of endothelium (p < 0.001)." (PMID 26910225, 2015). "When obesity persists for a long time, antioxidant sources can be depleted, decreasing the activity of enzymes such as superoxide dismutase (SOD) and catalase (CAT)." (PMID 21686173, 2011). "Obesity did not result in increased cardiac nitrosative stress, however increased expression of catalase and reduced the antioxidant enzyme MnSOD." (PMID 41334452, 2025). "The subjects with normal weight, overweight, and obesity who were positive for HAdV-36 showed low levels of catalase activity, compared with the subjects negative for HAdV-36." (PMID 40136420, 2025). "In obesity, there is an increase in pro-inflammatory cytokines, such as TNF-α, which can lead to ROS accumulation, inducing the expression of pro-oxidant enzymes (e.g., NADPH oxidase) and reducing the expression of antioxidant enzymes (e.g., catalase)." (PMID 40647324, 2025). "Collectively, Age, T2D, and obesity-related signaling pathways end at induction of oxidative stress and disruption of first-line defense Antioxidants-Superoxide Dismutase (SOD), Catalase (CAT), and Glutathione Peroxidase (GPX)." (PMID 40951640, 2025). "The activation of ROS detoxification by catalase overexpression preserved mitochondrial function, prevented the development of cardiac hypertrophy, and rescued heart function in mice with HFD-induced obesity." (PMID 39094772, 2024). "We showed that the overexpression of mitochondrial catalase within adipose tissue alone was not sufficient to confer systemic metabolic protection against diet-induced obesity." (PMID 37238003, 2023). "In this line, we reported that CAT, GSHR, and GPx could be the antioxidant enzymes that are majorly affected by IR in prepuberal children with obesity." (PMID 37672200, 2023). "Consistent with previous reports, at the molecular level, diet-induced obesity caused a decrease in antioxidant enzyme (SOD2 and catalase) mRNA expression without any change in pro-oxidant (NOX2) mRNA expression in murine aortas." (PMID 35073378, 2022).
Obesity (continued). "Likewise, the lipid peroxidation induced by obesity displays a substantial decrease in the level of the main antioxidant enzymes like SOD, GPx, CAT, and GSH." (PMID 36248416, 2022). "GPx responded to DM2 or DM2 and obesity in a similar manner as did SOD and CAT." (PMID 36405233, 2022). "Obesity have been reported to induce a collapse of the antioxidant defense mechanism characterized by diminishing activities of superoxide dismutase (SOD), catalase (CAT), and glutathione peroxidase (GPx) resulting in an accumulation of lipid peroxides and reactive oxygen species." (PMID 34122598, 2021). "This has been previously shown in mice lacking catalase, which develop obesity and a prediabetic phenotype." (PMID 33562490, 2021). "Our results demonstrate that WBC can influence antioxidative enzyme activity (CAT) but does not affect plasma antioxidant potential in people with extreme obesity." (PMID 33560197, 2021). "This material was reported to have anti-oxidative activity by increasing the levels of SOD, CAT, GST and decreasing TBARS level in liver and anti-obesity activity in HFD-induced mice or anti-obesity activity for inducing apoptosis in 3T3-L1 adipocytes, but few studies have examined these effects." (PMID 31109115, 2019). "We found that the depressor response to the ganglionic blocker pentolinium was augmented by fat feeding induced obesity in WT but not CAT+ mice." (PMID 26186712, 2015). "Of note, we found that obesity significantly augmented pressor responses to restraint, but not shaker or feeding stress, in CAT+ mice." (PMID 26186712, 2015). "When obesity persists for a long time, therefore, the antioxidant sources can be depleted, decreasing the activity of enzymes such as superoxide dismutase (SOD) and catalase (CAT)." (PMID 26171246, 2015). "Obesity increases the total reactive oxygen species and superoxide in brain, which might explain the decreased activities of SOD, catalase, and GPX observed in obese mice." (PMID 24163719, 2013). "Several studies have demonstrated that obesity could also deplete antioxidant sources, decreasing the activity of enzymes such as superoxide dismutase (SOD), glutathione peroxidase (GPx), and catalase (CAT)." (PMID 23819063, 2013). "The increment in renal catalase and MDA offer better understanding and evidence for the relation between obesity and oxidative stress where increased ROS levels generally stimulate antioxidant system as a compensated defense mechanism and are an important trigger for insulin resistance." (PMID 21235803, 2011). "Another SNP variation, SNP rs769214, was found to be significantly associated with insulin resistance, obesity, higher BMI Z-score, adipocyte fatty acid-binding protein (A-FABP) and with higher plasma insulin concentration, without any effect on erythrocyte CAT activity as well." (PMID 40428311, 2025). "Given this background, the aim of this work was to determine whether some male fertility problems that occur in overweight and obesity conditions are attributable to an alteration in the activity of the antioxidant enzymes SOD, GPX, and CAT in the testes and epididymides." (PMID 36263361, 2022). "According to the results of our study, obesity is not effective on the catalase activity." (PMID 35209038, 2022). "In addition, it is known that HFD-induced obesity leads to oxidative damage through lipid peroxidation by producing malondialdehyde, depleting endogenous antioxidants, and decreasing the activity of antioxidant enzymes such as SOD and CAT." (PMID 36500974, 2022). "- Anti-obesity, anti-hyperlipidemia, anti-hyperglycemia, anti-inflammation and anti-oxidation (↓body weight, ↓serum TG, TC, HDL-C, LDL-C, glucose, TNFa, MCP-1; ↑serum adiponectin; ↑liver GSH, SOD, CAT, T-AOC, GSH-Px; ↓liver MDA) in HFD-mice (10 mg/kg bw, p.o., 8 weeks)." (PMID 35769384, 2022).
Obesity (continued). "Researches showed that obesity induced oxidative stress and obesity may be a state of chronic oxidative stress, an increase in NO and MDA contents, and a significant decrease in activities of SOD, CAT, and GPx." (PMID 32104715, 2020). "Thus, high MDA and H2O2 levels, and low GSH, CAT, and GSH-PX levels, may contribute to the low levels of testosterone induced by obesity and DEHP in testicular tissue." (PMID 29887939, 2018). "The purpose of this adipose tissue catalase upregulation in obesity is not conclusively known, but, at least in animal models, adipose tissue catalase plays an important role not only in antioxidant defense but also in protection against obesity-associated inflammation." (PMID 28545081, 2017). "Both enzymatic (superoxide dismutase, catalase, glutathione peroxidase) and non-enzymatic (glutathione, vitamin E) antioxidant systems have been reported to be depleted in obesity, although there are differences in extent depending on the tissue and the degree of obesity." (PMID 29028831, 2017). "Interestingly, catalase activity, which is responsible for the degradation of excessive amounts of H2O2, has been shown to be decreased in obese adults as well as in children with obesity and insulin resistance." (PMID 27023799, 2016). "The effects of G. Cambogia on impaired ACh-stimulated vasodilation through restoring the brain NO level and decrease brain catalase and MDA compared to the HFD support the hypothesis that oxidative stress contributes to brain endothelial dysfunction in obesity." (PMID 21569551, 2011). "In our experimental model we have not detected modulation in SOD-2 or Catalase protein levels, therefore CR preserves the antioxidant enzymes proteins levels and probably through the modulation of their activity levels it counteracts the oxidative damage resulting from aging and obesity." (PMID 37760081, 2023). "Therefore, NAFL, but not obesity per se, was accompanied by the increased expression of NFE2L2 targets genes, including NOX4, which encodes a ROS-producing enzyme, and NQO1, SOD2, and CAT, which encode key antioxidant defense enzymes, but these declined with more advanced disease and fibrosis." (PMID 38060313, 2023). "The specific activities of CAT and GPX increased in the overweight and obesity groups, but those of SOD did not change." (PMID 36263361, 2022). "The expression of antioxidant enzymes, including catalase, superoxide dismutase I (SOD1), and superoxide dismutase II (SOD2), in the aorta was not significantly affected by obesity and pioglitazone treatment." (PMID 33781257, 2021). "It’s worth mentioning that between the low-does SIF group and the obesity group, that we witnessed no significant change in GSH-Px, and CAT activities, the content of GSH, and T-AOC levels." (PMID 31443330, 2019). "In the present study, we have shown that in obesity we can rescue the PVAT vasorelaxant effect by incubating the obese PVAT with the free radical scavengers SOD and catalase, and that this is not endothelium dependent." (PMID 26910225, 2015).
Hyperglycemia (129 papers, 2008 to 2026). An increased concentration of glucose in the blood. "The literature reviews indicated that low CAT activities in patients with T2D are consistently linked to T2D development and that hyperglycemia leads to the downregulation of CAT expression." (PMID 37432193, 2023). "Although the liver is equipped with antioxidant defenses, including GSH, SOD, and CAT, hyperglycemia-induced ROS generation was associated with diminished levels of these antioxidants as previously demonstrated." (PMID 31887984, 2019). "The results of the present study demonstrated that hyperglycemia notably increased the level of MDA in myocardial tissue and markedly decreased the activities of GSH-Px, SOD, and CAT, suggesting that hyperglycemia may cause severe oxidative stress injury in diabetic rats." (PMID 36597092, 2023). "While some studies have demonstrated elevated brain SOD and catalase activities in zebrafish and rodent models of hyperglycemia, others have observed the opposite." (PMID 41462586, 2025). "In this study, blueberry polyphenols diminished liver oxidative stress induced by hyperglycemia, which included increasing levels of the antioxidant enzyme catalase CAT and decreasing MDA levels, likely due to the antioxidant properties of polyphenols." (PMID 39765819, 2024). "The activity of the antioxidant enzymes SOD and CAT was increased in the obese group as an adaptive response or compensatory mechanism to minimize the overproduction of ROS due to hyperglycemia and IR, which generated oxidative stress." (PMID 39123622, 2024). ") linked to lipotoxicity (hyperglycemia and dyslipidemia) strongly activates SOD, which produces significant amounts of H2O2 (hydrogen peroxide) that cannot be completely eliminated by catalase and GPx, which explains their drop activities." (PMID 39273236, 2024). "Hyperglycemia also decreases antioxidant capacity by reducing the activities of superoxide dismutase enzyme 2, glutathione peroxidase, and catalase." (PMID 39202513, 2024). "Blackberry juice protected pancreatic beta cells from necrosis and apoptosis by decreasing lipid peroxide activity, enhancing catalase activity leading to a progressive recovery of insulin output, and improved management of hyperglycemia." (PMID 37280499, 2023). "AuNPs partially recuperated the antioxidant defense, particularly catalase activity, and inhibited the IL1β proinflammatory cytokine release induced by hyperglycemia." (PMID 37627484, 2023). "In this study, the diabetic group showed a decrease in catalase and MnSOD activity, which is consistent with other studies that have reported that during hyperglycemia or steatosis, both enzymes showed a decrease in their activities." (PMID 37371966, 2023). "Results revealed hyperglycemia, hypoinsulinemia, increased MDA, TNF-α, IL-6, and NF-κB levels, in association with reduced CAT, SOD, GSH, Nrf2, and HO-1 levels in LCT group." (PMID 37463968, 2023). "So, the increased activity of SOD and CAT observed in the present study can be interpreted as a compensatory response against hyperglycemia-induced OS." (PMID 35434481, 2022). "On the other hand, GPx activity was significantly higher in the DMC group than in the NOC group and appeared to depend on increases in H2O2 concentrations by hyperglycemia and decreases in catalase activity." (PMID 36009274, 2022). "Hyperglycemia was reported to alter MnSOD and catalase activities in a cell-dependent manner: it downregulates MnSOD and catalase in human umbilical vein ECs but not in microvascular EC." (PMID 33445766, 2021). "We found that two anti-oxidant proteins (SOD2 and CAT) were decreased in 16-week-old diabetic mice, along with severe hyperglycemia and low insulin levels." (PMID 34249264, 2021).
Hyperglycemia (continued). "In summary, our data indicated that NBP administration reduced the hyperglycemia- related oxidative stress damage, which was associated with enhanced expressions of Nrf2, and its downstream antioxidants TRX and catalase in the lens of diabetic rats." (PMID 26759189, 2016). "Hyperglycemia-induced oxidative stress was assessed by measuring the activity of antioxidant enzymes CAT, GPx, and SOD in erythrocyte lysates and by determination of serum nitrotyrosine levels using western blot analysis." (PMID 25243053, 2014). "Although the antioxidant supplementation did not interfere on MDA levels, the oxidative stress caused by chronic hyperglycemia was reduced by increasing SOD and restoring CAT and GPx activities." (PMID 24982856, 2013). "Curcumin abates oxidative stress due to reactive oxygen species and lipid-peroxidation by reducing hyperglycemia, and enhancing endogenous antioxidant machinery (glutathione peroxidase, catalase, superoxide-dismutase, and reduced glutathione, and GSH)." (PMID 24279645, 2013). "Decreased values of GST, SOD, and CAT were estimated in G2 when hyperglycemia was induced." (PMID 38577302, 2024). "Furthermore, hyperglycemia led to a reduction in key mitochondrial antioxidant enzymes, including catalase, glutaredoxin, thioredoxin reductase (TrxR), and peroxiredoxin." (PMID 38818468, 2024). "Besides this, hyperglycemia aggravates oxidative stress through the alteration of endogenous antioxidant systems notably, the inactivation of antioxidant enzymes such as catalase, GSH, GPx, and SOD." (PMID 36832834, 2023). "Furthermore, our study showed that alloxan-induced hyperglycemia has altered the enzymatic antioxidant status by a reduction in the most critical antioxidant enzymes (catalase, GSH, and GPx) synthesis in organs." (PMID 36832834, 2023). "Ce@LTA-NPs showed the ability to mimic the catalytic activities of superoxide dismutase (SOD) and catalase (CAT), thus eliminating free radicals including ROS induced by hyperglycaemia and regulating the oxidative state in the microenvironment of the wound site." (PMID 34895257, 2021). "Oxidative stress is depicted in this study by the reduced levels of GSH, SOD and catalase activities in the muscle tissues and may be attributed to hyperglycemia-induced generation of free radicals." (PMID 34548565, 2021). "Male: ↑systolic blood pressure, hyperglycemia, hypertriglyceridemia, insulin resistance and serum igf1 concentrations; ↑lipid peroxidation and catalase activity; rehabilitation reversed the effects female: less sensitive to the metabolic effects of zinc restriction." (PMID 34746215, 2021). "Compared with the LECs in normal mice, there were increased expressions of the oxidative stress markers of SOD2 and CAT in the cells subjected to hyperglycemia in the first 2 months, but an obvious reduction at 4 months, which was in line with a previous study about the corneas of diabetic mice." (PMID 32186721, 2020). "In the present study, women had significantly higher basal glycemia compared with men, which supports the hypothesis that the increased catalase in women is the result of an adaptive mechanism to the oxidative stress enhanced by hyperglycemia." (PMID 32512870, 2020). "Hyperglycaemia diminished the activities of CAT, GPx and SOD compared to the controls." (PMID 31892189, 2019). "Hyperglycemia increases the thickness of capillary basement membrane in the nerve fiber layer and the outer plexiform layer, which leads to retinal capillary cell apoptosis, reduced activity of retinal dismutase and catalase." (PMID 29785346, 2018). "In addition, the extract minimized oxidative damage to lipids and proteins, caused an imbalance in the antioxidant enzyme activities of superoxide dismutase and catalase, and decreased the nitric oxide levels induced by hyperglycaemia." (PMID 30018977, 2018).